ALB (albumin)
Diseases named in the same sentence as ALB in open-access papers (continued):
Sharing a sentence is not in itself a finding about the gene and the disease.
anemia (continued). "There were abnormalities in seven cases (one case with increased PCV, one with leucocytosis, one with decreased neutrophils, one with mild anaemia, one with increased albumin, one with increased lactate, and one with increased ACTH and AST relating to existing endocrine disease)." (PMID 25238179, 2014). "HIV-MCD presents with various clinical symptoms, including fever, swelling of the spleen, liver and systemic lymph nodes and abnormalities in laboratory values, such as findings of anemia, thrombocytopenia or hypergamma-globulinemia, as well as a low albumin, or high C-reactive protein (CRP) level." (PMID 24438824, 2014). "Numerous studies have documented that an increased risk for death and hospitalization was associated with lower levels of dialysis adequacy, increased anemia, lower serum albumin values, and the use of a vascular access other than an arteriovenous fistula (AVF) for hemodialysis." (PMID 23705852, 2013). "FFA concentrations are altered for several days after different food choices, and albumin may decrease with emesis or anemia." (PMID 22496600, 2012). "In addition to the risk of ESRD, anemia was associated with male sex, older age, lower eGFR, higher SBP, more severe proteinuria, higher uric acid level, lower albumin level, and more severe Haas class." (PMID 22719981, 2012). "Gender, age, smoking status, comorbidity, general health status (e.g. performance status), anaemia, peripheral oedema, serum albumin and creatinine levels and the frequency and severity of respiratory failure varied widely between patients treated in different hospitals." (PMID 22911875, 2012). "In HD patients iron deficiency without evidence of iron deficiency anemia has been reported, and IV iron repletion was associated with positive effects on serum albumin, muscle mass, hospitalization, and blood pressure." (PMID 19245700, 2009). "Unexpected findings included: a very significant rise in serum albumin – an excellent outcome marker – and in indirectly measured muscle mass; iron deficiency without iron deficiency anemia; decreased hospital admissions and stay." (PMID 18045495, 2007). "After adjusting for age; sex; race/ethnicity; body mass index; smoking status; and levels of albumin, creatinine, ferritin, and transferrin receptor, a nonlinear (U-shaped) association was observed between Mn levels and anemia risk (P < 0.001 for nonlinearity)." (PMID 40740730, 2025). "Our analysis additionally identified NT-proBNP, albumin, troponin I, and hemoglobin levels as important prognostic factors, reinforcing the necessity of comprehensive clinical management addressing volume status, cardiac function, anemia and nutritional status." (PMID 40217720, 2025). "Subsequent treatment involved 20% albumin over 12-hour infusions (2 g/kg/day) to support intravascular volume and reduce extravascular fluid retention when symptomatic hypovolemia was suspected and red blood cells transfusion due to anemia, as evidenced by hemoglobin of 5.9 g/dL." (PMID 38808020, 2024). "For example, some studies in their meta-analysis showed that the benefits of early referral, such as lower mortality after commencement of KRT, could be attributed to the early referred patients having lesser degree of anaemia, higher pre-dialysis albumin, and better pre-dialysis BP control." (PMID 38689219, 2024). "Changes in the metabolic function may lead to anemia, low albumin, low potassium and others." (PMID 37202743, 2023). "In this report, we explored the association between LRG1 and anemia in children by assessing the correlation between LRG1 and several iron deficiency markers, including hemoglobin, iron, percentage of transferrin saturation, ferritin, albumin, and red cell distribution width (RDW)." (PMID 37513518, 2023). "It is not coincidental that serum albumin levels have been claimed to be independently associated with severe anemia and could influence mortality and the outcome of HAART in HIV patients." (PMID 37575113, 2023).
anemia (continued). "Our study demonstrates that the rate of mortality is significantly higher in Group S and Group I compared with the Group N. As opposed to the previous study, preprocedural serum albumin level or preprocedural anemia were not risk factors for poor survival at 1 year." (PMID 36590743, 2022). "In the case of liver injury, a decrease in albumin and total protein are commonly observed, but the decreased HCT and increased albumin concentration observed, together with the increase in total protein concentration, could point to a serious anemia and dehydration." (PMID 36050419, 2022). "It is possible that our sample size may not be large enough to detect these as risk factors for poor survival at 1 year, which may suggest that the 5-m walk test may be a more sensitive indicator or early sign of frailty than either serum albumin level or preprocedural anemia." (PMID 36590743, 2022). "Furthermore, anaemia was significantly more prevalent amongst subjects requiring intervention than in the self-healing group (p < 0.03), while haemoglobin, iron, ferritin, and albumin levels were lower (p < 0.001, p < 0.05, p < 0.02, p < 0.007, respectively)." (PMID 34682146, 2021). "Few studies that examined anemia have addressed potential predictors or factors associated with anemia such as age, sex, family history of IBD, clinical disease activity, and inflammatory biomarkers, such as high C-reactive protein (CRP), erythrocyte sedimentation rate (ESR), and albumin." (PMID 33467587, 2021). "The TEAE more frequently reported among patients who were more severely ill in the pivotal trial might be attributed to the disease itself and include back pain, increase in blood potassium, anaemia, decrease in blood albumin, chest pain, cough, pyrexia, or hypocalcaemia." (PMID 34143998, 2021). "Logistic regression analysis using model 3 showed that age ≥65 years, female sex, albumin level ≤3.5 g/dl, difference between sodium and chloride concentrations (Na–Cl) ≤30 mEq/L, and CRP level ≥0.3 mg/dl were also independent risk factors for increased prevalence of anemia (JSDT2 Criteria)." (PMID 32687544, 2020). "None of the patients had B12 deficiency, anemia or low albumin levels." (PMID 32414050, 2020). "On the other hand, anemia and reduced plasma volume are common in severely malnourished patients with AN; thus, even if albumin hepatic synthesis was marginally reduced, this may match with the reduction of plasma volume and lead to apparently normal concentration." (PMID 28257095, 2017). "Therefore, it could be suggested that the association between HRQoL and GFR may also be influenced by other factors such as anemia, nutritional status, and albumin among others." (PMID 26131714, 2015). "In adjusted analysis, albumin, age, gender, platelet-neutrophil ratio, kidney disease, ICU admission, and MATH-1SD were independent predictors of anemia." (PMID 42194507, 2026). "Hemoglobin-to-red cell distribution width ratio (HRR) and creatinine-to-albumin ratio (CAR) are simple and easily obtainable biomarkers reflecting anemia/inflammation and renal and nutritional status, respectively." (PMID 42111161, 2026). "Conversely, the negative associations observed with clusters reflecting anemia and nutrient availability (hemoglobin, albumin, calcium, and HDL) could indicate a general systemic insufficiency in nutrient intake, absorption, or utilization, potentially amplified by chronic low-grade inflammation." (PMID 41305594, 2025). "The bloodwork revealed anemia with a packed cell volume (PCV) of 28% (reference range: 35–45%), with normal TPP of 74 g/L (reference range: 60–79 g/L) and serum albumin of 24 g/L." (PMID 40538723, 2025). "We found that DM duration, obesity, FPG, TG, Scr, eGFR, BUN, serum albumin, urinary protein in 24h, FIB, use of ACEI/ARB, anemia, hypocalcemia, MetS, number of MetS components, glomerulosclerosis rate, IFTA scores were risk factors for T2DN progression." (PMID 40810070, 2025).
anemia (continued). "Altered lymphocyte count, serum albumin, and transferrin levels is common among individuals undergoing TKA, particularly in older patients, those with anemia, and individuals with normal or low weight." (PMID 40727701, 2025). "Kidney-related parameters (e.g., eGFR, BUN, and UA), anemia-related parameters (e.g., MCHC and MCH), and serum albumin were included in the classification models." (PMID 39762534, 2025). "Higher levels of ALB and HGB reflect improvements in the general condition and anemia, respectively, while lower PLT values suggest a reduction in the inflammatory response." (PMID 40386079, 2025). "Nineteen indicators relevant to the anemia prediction model for patients with osteosarcoma after chemotherapy were identified, including Gender, Surgery, LYM, MO, LYM%, BLT, TP, ALB, CA, CREA, APTT, FIB, D‐dimer, CRP, ESR, PCT, IgA, CEA, and CA.153." (PMID 39621534, 2024). "TC, albumin, and TIBC are affected by nutrition and inflammation status as well as by liver function and anemia." (PMID 37726432, 2024). "The most common laboratory abnormalities seen in hospitalized COVID-19 patients include lymphocytopenia accompanied by an elevated neutrophil count, thrombocytopenia, anemia, raised LDH levels, D-dimer, CRP, liver enzymes, and decreased albumin levels." (PMID 37712883, 2024). "Laboratory tests revealed that the median lowest hemoglobin was 67 (IQR, 49-81) g/L and the median lowest albumin was 28 (IQR, 22-33) g/L, suggesting anemia and hyperalbuminemia." (PMID 38755710, 2024). "Supportive laboratory investigations showed anemia for age, raised inflammatory markers (CRP-20.5 mg/dl, ESR-63 mm 1st hour), hypoalbuminemia (serum albumin-2 g/dl), hyponatremia (serum sodium-126 meq/L), and pyuria (8-10 Pus cells) typically suggestive of KD." (PMID 38975482, 2024). "On the other hand, in our study patients with severe pneumonia requiring PICU admission had greater anemia and lymphopenia, higher PCT and LDH values, as well as lower levels of albumin and HDL cholesterol." (PMID 37892366, 2023). "In the PEG group, more patients had ≥35 g/L albumin level (PEG: 98.4%, NTF: 88.9%, ONS: 81.0%, p = 0.006) and had less incidence of grade ≥3 anemia (PEG: 3.2%, NTF: 7.9%, ONS: 6.3%, p = 0.074) during treatment." (PMID 37326436, 2023). "Patients who required non-invasive ventilation (NIV) had greater anemia (p = 0.003) and lymphopenia (p = 0.005), higher values of PCT (p = 0.008) and LDH (p = 0.006) and lower levels of albumin (p = 0.008) and HDL cholesterol (p = 0.012)." (PMID 37892366, 2023). "Relative to the non-anemia group, there were more black patients, female subjects, low education level, low total levels of cholesterol, eGFR, albumin, serum iron and SUA, higher age, UACR and BMI in the anemia group." (PMID 37291524, 2023). "A previous study found that the severity of depression was positively correlated with C-reactive protein and ferritin levels and negatively correlated with serum albumin levels, suggesting that ESRD patients with depression also have anemia and inflammation." (PMID 36825130, 2023). "Among the laboratory abnormalities, the most common is the occurrence of lymphopenia with an increased number of neutrophils, thrombocytopenia, anemia, and elevated values of LDH, AST, ALT, CK, D-dimer, CRP, and decreased albumin values." (PMID 37510752, 2023). "In our study, 55.6% of patients had an ALB<35 g/L, 91.4% had an ESR>20 mm/h, and 59% had anaemia, which was predominantly mild." (PMID 37651639, 2023). "Univariate COX analysis revealed that age, sex, BMI, smoke, stage, albumin, ALI, anemia, KPS, NRS 2002, surgery, and radiotherapy all affected the prognosis of patients with lung cancer cachexia." (PMID 35898878, 2022). "Preoperative BUN, serum albumin, alanine serum transferase (AST), relative leukocytosis, relative anemia, thrombocytopenia, and PTT were significant univariate predictors of mortality and ICU-level complications." (PMID 36503680, 2022).
anemia (continued). "Laboratories disclosed anemia, thrombocytopenia, elevated erythrocyte sedimentation rate (ESR) and C-reactive protein (CRP), albumin-globulin (A-G) reversal, and sterile blood cultures." (PMID 36654579, 2022). "Serum albumin level represents the protein storage of internal organs, and red blood cells are a routine examination item for diagnosing iron deficiency anemia, and hemoglobin is commonly used to diagnose anemia caused by lack of hematopoietic substances or utilization disorders." (PMID 35310190, 2022). "Bovine serum albumin-nanoparticles (BSA-NPs) of iron (Fe) and folic acid (FA) can be recommended as anti-anemia supplements in different functional food applications." (PMID 33898503, 2021). "They include SAPS II, renal replacement therapy, temperature, SpO2, albumin, INR, lactate, respiratory failure, urinary tract infection, anemia, systolic blood pressure (sysbp), partial thromboplastin time." (PMID 34489922, 2021). "Final statistical analysis identified 12 predictors for SA-AKI, including BMI, LOS in ICU, baseline SCr, glucose, anemia incidence, CKD, heart failure, coronary disease, chronic liver disease, and the use of human albumin or vasoactive drugs." (PMID 33971853, 2021). "Based on obtained results, bovine serum albumin-nanoparticles (BSA-NPs) of iron (Fe) and folic acid (FA) can be recommended as anti-anemia supplement in different functional food applications." (PMID 33898503, 2021). "At presentation, CD patients showed significantly more anemia, higher C-reactive protein (CRP) levels, and low proportion of albumin <3.5 g/dL compared with UC patients." (PMID 37206943, 2021). "Other studies showed that patients presented with anemia, lymphopenia, thrombocytopenia, slightly abnormal creatinine and BUN levels, low albumin levels, high d-dimer, CRP, and procalcitonin levels." (PMID 34945730, 2021). "Laboratory findings like anemia, elevated ALP and LDH, reduced albumin, elevated ESR, CRP along with increased serum ferritin also suggest the possibility of AOSD." (PMID 32335625, 2020). "According to the results of the multivariate logistics regression analysis, we used WBC, anemia, PCT, CRP, albumin, and ALT to develop the nomogram model." (PMID 32792679, 2020). "We compared these five cytokines/GFs concentrations between the patients with and without the negative clinical prognosis factors for MAC-LD (low BMI, low albumin, high CRP and anemia)." (PMID 30885152, 2019). "Surgery resulted in anaemia, leucocytosis, lymphopenia, thrombocytosis, rise in neutrophils, CRP, erythrocyte sedimentation rate (ESR) and a reduction in albumin levels." (PMID 29490633, 2018). "or hemoplasma infection, anaemia and hemoplasma infection, elevated ALP serum activity or low albumin concentration and A. phagocytophilum antibody positivity, high globulin concentration and Bartonella spp." (PMID 29554931, 2018). "Close associations between elevation of cytokine levels in the plasma and presence of B symptoms, anemia, leukocytosis, high ESR and low serum albumin levels has been reported." (PMID 28291005, 2017). "Thus, we could speculate that the effects of the IL-6 system on frailty, especially sarcopenia, may involve their contribution to lean body mass decrease, bone mineral density decrease, anemia, thrombocytosis, cholesterol and albumin decrease, insulin resistance, and cognitive impairment." (PMID 27119508, 2016). "Those diagnosed with active TB within 96 weeks of ART initiation were five times as likely to have low albumin and two to three times as likely to have highest-quartile levels of CRP and IP-10, detectable plasma LPS, and anemia." (PMID 25719208, 2015). "To minimize the effects of erythrocytes or albumin turnover on HbA1c or GA values, we excluded subjects who had liver cirrhosis or CKD, pregnancy, steroid therapy, and hematologic disorders such as anemia." (PMID 25265016, 2014).
anemia (continued). "At week 5 of corticosteroid therapy, another relapse occurred (7 to 8 stools daily, anemia 6g/dL, ESR 40mm, albumin 17g/L) and we had considered that it was a refractory severe UC." (PMID 24396560, 2013). "Baseline MDRD values were 36 vs. 40 mL/min and albumin 4.1 vs. 4.3 g/dL; reduction in MDRD was greater in those that developed anemia (6.8 vs. 1.6 mL/min/1.73 m2/3 years)." (PMID 23295149, 2013). "Regarding laboratory tests, anaemia (defined as haemoglobin ≤ 10 g/dL) was detected in 12.3% of the patients, ESR ≥ 30 mm/hour in 18%, platelets count > 400.000/mm3 in 35.9%, and albumin ≤ 3.0 g/dL in 3.2%." (PMID 23213555, 2012). "Laboratory findings in severely malnourished children include low albumin, protein, prealbumin, BUN, cholesterol, transferrin, ferritin, B12, folate, and lymphocyte count and severe anemia." (PMID 16412249, 2006). "In this study, we found that the albumin levels were markedly lower in the anemia group than that in the non-anemia group (p < 0.05)." (PMID 41550749, 2026). "In our retrospective study, we demonstrated that the albumin levels were significantly lower in the anemia group than in the non-anemia group (p < 0.05)." (PMID 41550749, 2026). "Reduced anemia and numerically lower fecal calprotectin levels suggest attenuation of certain inflammatory or bleeding-related components of DSS injury, whereas increased albumin and a tendency toward mucosal erosion indicate greater epithelial compromise." (PMID 41472066, 2025). "The Hemoglobin, Albumin, Lymphocyte and Platelet (HALP) score, calculated as hemoglobin × albumin × lymphocytes / platelets, serves as a novel biomarker that can provide insights into a patient's nutritional status, anemia status and inflammatory processes." (PMID 39838526, 2025). "Lastly, albumin levels were lower in both males and females with anemia compared to those without anemia (males: 39.8 ± 6.2 vs. 42.6 ± 7.9 kg/m2; females: 40.4 ± 6.8 vs. 42.0 ± 7.1 kg/m2, p < 0.05)." (PMID 40063574, 2025). "Recurrent rashes for 12 years, with hypokalemia, elevated lactate, mild to moderate anemia, negative for lupus erythematosus, and liver function showing decreased albumin." (PMID 40129607, 2025). "The Hemoglobin, Albumin, Lymphocyte and Platelet (HALP) score has garnered attention recently as a scoring system that provides information about patients' nutritional status, anemia status, and inflammatory processes." (PMID 39838526, 2025). "Body weight, plasma glucose, triglyceride, LDL and non-HDL cholesterol levels, eGFR, plasma albumin and total protein concentrations, and anemia parameters, showed a weak negative correlation with age." (PMID 39685592, 2024). "After six weeks of CPF exposure, fish suffered from anemia as red blood cell count (RBCs), hemoglobin (Hb), and packed cell volume (PCV) significantly declined along with downregulation of serum total protein (TP), globulin (GLO), and albumin (ALB)." (PMID 38722391, 2024). "Patients with anemia had greater prevalence of DKD, higher levels of urinary albumin-to-creatinine ratio (UACR), serum creatinine, BUN, urine α1-MG, urine β2-MG, urine NAG/Cr, hsCRP, Cystatin C, homocysteine and lower eGFR, as compared to the patients without anemia." (PMID 36755908, 2023). "Regardless of the degree of disease activity, most of the population did not have anemia and had adequate albumin levels." (PMID 36839908, 2023). "Our findings demonstrate a positive correlation between serum albumin, prealbumin, and IGF-1 levels, indicating that the impact of IGF-1 on nutrition may also play a role in anemia." (PMID 37403637, 2023). "The second stage was initiated 2 days after noting improvements of the patient’s general condition, such as good mental state and no obvious anaemia (haemoglobin ≥ 100 g/L) or hypoproteinaemia (albumin 35 g/L)." (PMID 38082020, 2023).